ABCG2 (ATP binding cassette subfamily G member 2 (JR blood group))
Diseases named in the same sentence as ABCG2 in open-access papers (continued):
Sharing a sentence is not in itself a finding about the gene and the disease.
tumor (continued). "Moreover, inhibition of the EGFR/HER2 signaling axis by lapatinib blocked the expression of ABC transporter proteins, ABCB1 and ABCG2, which sensitizes MCF-7 tumor spheres to doxorubicin." (PMID 35392236, 2022). "Human tumor transcriptomic data for 377 HCC patients also show a positive correlation of multiple ABC transporters including the ABCB1, ABCC3, ABCC9 and ABCG2 with GHR expression, while ABCC1,ABCC4 and ABCG1 levels correlated with IGF1R expression, confirming our in vivo observations." (PMID 35865483, 2022). "We hypothesize that drugs targeting ABCG2 and stemness in SCLC will address the subpopulation of tumor cells that promote recurrence." (PMID 35804016, 2022). "Although some studies have reported non-significant upregulation of ABCG2 mRNA in HCC, in general, BCRP expression is higher in tumor tissue than in adjacent non-tumor liver tissue and healthy hepatocytes." (PMID 35884584, 2022). "Interestingly, squamous cell markers such as SALL4, NANOG, SOX2, BMI1, OCT3/4, HIWI, ABCG2, CD133, podoplanin, and ALDH1 also correlate with ESCC tumor stages, therapeutic resistance, relapse, and patient prognosis." (PMID 36474162, 2022). "Up regulation of ATP-binding cassette(ABC) transporter super family proteins such as ABCB1, ABCG2 and ABCC1 which pump chemotherapeutic drugs out of tumor cells thereby reducing intracellular drug accumulation have been observed as the most common mechanism of chemotherapy resistance." (PMID 37654838, 2022). "Interestingly, several BBB-related transporters, including SLC2A1, ABCG2, ABCB1, SLCO1A2, and ATP10A were significantly decreased in ECs in tumor core." (PMID 34228647, 2021). "It has shown downregulation of P-gp, BCRP, MRPs, and ABC transporter genes (ABCB1, ABCG2, and ABCC1), which may reverse MDR in tumor cells." (PMID 34680470, 2021). "Quercetin has been also reported to modulate the activity of some members of the multidrug-resistance transporters family, such as P-gp, ABCC1, ABCC2, and ABCG2, and the activity of ecto-5′-nucleotidase (NT5E/CD73), a key regulator in some tumor processes such as invasion, migration, and metastasis." (PMID 33918012, 2021). "Analysis of the tumor microenvironment regulating CSCs revealed that the factors in CSC-niche activates effector molecules that function as CSC markers, including pluripotency markers, CD133, ABCG2 and ALDH1A1." (PMID 33968778, 2021). "For the castration-induced regression nadir group (i.e., those with the weakest or most unsuccessful castration-induced tumor regression), GSE1, CYP3A5, CTNNB1, CYP3A4, POU5F1, ABCB1, alkaline phosphatase liver/bone/kidney isozyme (ALPL), PROM1/CD133, ABCG2, and SOX2 were concomitantly upregulated." (PMID 34439112, 2021). "Interestingly, PDE inhibitors were shown to inhibit several MDR transporters (e.g., ABCC4/MRP4, ABCC5/MRP5, ABCB1/P-gp, ABCG2/BCRP), thus enhancing chemotherapeutic drug accumulation in tumor cells and efficacy." (PMID 35008687, 2021). "Nestin, KLF4, ALDH1, EPCAM as well as ABCG2 expression was incongruous, with no clear relation to the four different parental tumor groups." (PMID 33800955, 2021). "Two efflux transporters from the ATP-binding cassette (ABC) family, ABCB1 and ABCG2, may contribute to MDR by restricting the entry of therapeutic drugs into tumor cells." (PMID 31729540, 2020). "The ABCB1 but not the ABCG2 promoter methylation status was significantly higher in tumor tissues than in healthy brains serving as controls." (PMID 33066132, 2020). "Additionally, eight genes (ABCG2, ALDH3A1, FXYD2, GST-π1, GST-ω1, HMGCR, MGST1, and MGST3) were upregulated among the G1-G4 DDP-resistant tumor tissues." (PMID 32158694, 2020).
tumor (continued). "In order to investigate the effect of EC16-1/saporin on the ABCG2-overexpressing tumors, the parental (NCI-H460) and ABCG2-overexpressing (NCI-H460/MX20) cells were implanted into athymic nude mice to create the ABCG2-overexpressing tumor xenograft model." (PMID 32098067, 2020). "Surprisingly, as the passage of the tumor-derived cells (TDCs) increased, the expressions of stem cell markers such as Oct4, CD133, and Sox2 decreased rapidly while the expression levels of oncogenes including c-Myc, Klf4 and ABCG2 were maintained." (PMID 31727938, 2019). "FL118 had a stronger negative effect on tumor growth compared to irinotecan in xenograft models that highly expressed ABCG2." (PMID 31443516, 2019). "The expression levels of these genes were not or hardly affected by PBF in tumor tissue, with the exception of Abcg2 which was downregulated due to PBF." (PMID 31040913, 2019). "Knockdown of ABCG2 using siRNAs and inhibition of ABCG2 using Ko143 decreased the SP rate, whereas knockdown of ABCG2 and inhibition of ABCG2 did not decrease sphere formation, indicating that ABCG2 expression is not related to tumor formation." (PMID 31083682, 2019). "It is interesting to note that both etoposide and teniposide are also recognized by ABCG2, and etoposide is additionally recognized by ABCB1, which may mask the OATP2B1-mediated effect in tumor cells expressing several transporters." (PMID 30863990, 2019). "Furthermore, the expression of stemness genes ABCG2, Nanog, Notch1 and Oct4 as well as Wnt-related genes CCND1, c-Jun, VEGF, and c-myc in tumor xenografts was down-regulated in shRab37 + rSFRP1 group (symbols pink vs. red)." (PMID 30158579, 2018). "The immunohistochemical analysis of the tumor samples confirmed our hypothesis that the combination treatment suppressed the WNT and β-catenin signaling, in addition of ABCG2 and increased Bax expression." (PMID 30005681, 2018). "Considering the gefitinib concentration in NSCLC tumor tissues is more than 40-fold higher than plasma levels, we speculate that ABCC10 may play a more important role than ABCG2 in acquired resistance to gefitinib in vivo." (PMID 30515095, 2018). "The authors proposed that the apparent increase in tumor ABCG2 expression was actually due to increased expression in the tumor vasculature, not the tumor." (PMID 29186899, 2017). "Since ABCB1 and ABCG2 are the major drug-efflux transporters at the BBB, that are highly expressed in Group 3 MB and MYCN-amplified SHH-MB, it would be beneficial to determine if these transporters are expressed at the tumor ECs of the various MB subgroups." (PMID 29186899, 2017). "Many studies have reported that the three monomers of curcuminoids reverse the overexpression of ABC transporters including ABCB1, ABCG2, and ABCC1 in drug resistant tumor cells without causing systemic toxicity." (PMID 28591733, 2017). "The specific stem cell markers ALDH1A (in keeping with the IHC result), ABCG2, and FGF1 were consistently and significantly over-expressed (all p values < 0.05) in the invasive margin of GBM when compared to rim and core tumour regions from where samples are conventionally taken." (PMID 29156557, 2017). "Along with this observation of data mining, we found through IHC detection that ABCG2 presents an obvious higher expression level in tumor tissues of the 72 GC patients compared with the non-cancerous adjacent tissues." (PMID 28029654, 2017). "We observed that expressions of both SOX2 and ABCG2 were higher in mammospheres as compared to the adherent cells, indicating enhanced expression of the respective genes in the CSC compartment of human tumor tissues." (PMID 28835684, 2017). "Compared to tumor-engraftment generated by PANC-1 cells grown in glucose-containing medium, ductular lesions in the tumor engraftment generated by PANC-1 cells grown under fructose-substituted conditions expressed higher levels of GLUT5, ABCG2, and CD133." (PMID 28032597, 2017).
tumor (continued). "Consequently, SOX2 was silenced in mammospheres, formed from human tumor tissues which resulted in down regulation of OCT4, NANOG, ALDH1A1, and most importantly, ABCG2 expression (p < 0.01), confirming a direct correlation of SOX2 with ABCG2." (PMID 28835684, 2017). "Expressions of SOX2, OCT4, WNT, NANOG, ABCG2 and ALDH1A1 was assessed both at transcriptional and translational levels from spheroids and sorted populations of CD44+/24− and ALDH+ cells of CT-TNBC tumor (CSC) versus the whole tumor." (PMID 28835684, 2017). "In brief, these studies clearly stated the key role for ABCG2 in general tumor cell survival independent of its well-characterized drug efflux function." (PMID 28059154, 2017). "Unexpectedly, IHC revealed only ABCG2 staining in the tumors microvessels, but not in the tumor cells." (PMID 29186899, 2017). "Currently, there are 48 known transporters in the ABC family, and 13 of the ABC transporters are related to tumor drug resistance, including P-glycoprotein (P-gp, MDR1/ABCB1), multidrug resistance proteins (MRPs/ABCCs), and breast cancer resistance protein (BCRP/ABCG2)." (PMID 28864784, 2017). "To figure out whether the expression level of ABCG2 was changed in xH460/MX20 cell xenografts, firstly, we isolated xenograft cells from H460/MX20 tumor xenografts as described in the Materials and Methods section, named xH460/MX20 cells." (PMID 28059154, 2017). "Immunohistopathological examination revealed a significant higher expression of ABCG2 in 63% (45/72) GC tumor specimens than the adjacent non-cancerous tissues." (PMID 28029654, 2017). "Our study further examined the effect of LT-NNK exposure and demonstrated upregulation of two of the most significant chemoresistance genes, MDR1 and ABCG2, and increased Oxaliplatin-induced chemoresistance, suggesting LT-NNK exposure also facilitates tumor progression." (PMID 26992205, 2016). "On the mechanism, we believe that BDNF itself does not affect tumor growth, but can reduce hypoxia of tumor, thereby reducing the ABCG2 expression." (PMID 27852063, 2016). "Previous studies that focused on phenotypic characterization of tumor-propagating cells have used various cell surface markers known to induce stem-like and mesenchymal phenotypes and/or drug resistance, such as CD117, Stro-1, CXCR4 and ABCG2, and CD133." (PMID 27634875, 2016). "However, ABCG2, like CD446, is correlated with stem cell behavior in tumor cells because it can actively drive some of the characteristics that define these cells." (PMID 27456282, 2016). "In their work, staining was regarded as positive if >10% of tumor cells were stained, and they observed ABCG2 expression in CRC but did not differentiate between cytoplasmic and membrane staining." (PMID 27257141, 2016). "This is certainly the case in our tumor models, since the clinically critical stem cell characteristics of in vivo tumor formation and radiation resistance were not affected by ABCG2 function." (PMID 27456282, 2016). "Next, we examined by qRT-PCR if FOXC2 knockdown in U2OS cells affects the expression of several genes known to be enriched in tumor-propagating cells, such as the cell surface marker CD133, multidrug resistance pump ABCG2, Notch signaling receptor ligands JAG1 and BMP4, and chemokine receptor CXCR4." (PMID 27634875, 2016). "Finally, we confirmed the ability of 4-HPR to target the BTIC component within the tumor mass, as showed by the CD133+ and ABCG2+ reduced cell percentage in the excised tumors from treated animals." (PMID 27367907, 2016). "In aggregate, the functional connections of Wnt activation with increases in tumor generation, metastasis, self-renewal, standard PCSC markers (CD133, CD44, and ABCG2), and pluripotency genes (OCT4 and NANOG) strongly support an important role of the Wnt/β-catenin signaling in promoting PCSLCs." (PMID 26593949, 2015). "We further analyzed the excised tumor for series of CSC markers (CD44, CD24 and ABCG2)." (PMID 26176230, 2015).
tumor (continued). "To show ABCG2 directly influenced PDT efficacy, we established SW480 stably overexpressing ABCG2 and also tested PDT efficacy using in vitro system, and then we checked the anti-tumor effect on xenograft model using cells differently expressing ABCG2 in vivo studies." (PMID 26149077, 2015). "High expression of ABCG2/BCRP1 in SP cells is contributed to drug resistance and tumor recurrence." (PMID 24418020, 2014). "RT-qPCR analysis on elderly HCCs demonstrated that the high expression levels of 7 putative hepatic stem/progenitor cell biomarkers (including keratin 19 (K19), ABCG2, CD44, Nestin, CD133, EPCAM and OV6), is related to tumor angiogenesis and a poor prognosis for the HCC." (PMID 24160375, 2013). "As far as we know, the ABC transporter-subfamily B member 1 (ABCB1/MDR1/P-glycoprotein, P-gp), subfamily C member-1/2 (ABCC-1/2, MRP-1/2), subfamily G member 2 (ABCG2, BCRP), and lung resistance-related protein (LRP) play a major role in producing MDR in tumor cells." (PMID 23533531, 2013). "DKK3 down-regulated stem markers such as NANOG, ABCG2 and OCT4, thus may reverse the stem cell-like phenotype of tumour cells." (PMID 23890219, 2013). "Note that ABCB1 and ABCG2 gene expression from baseline (untreated) cell line tumor xenografts was used for this analysis and not the cell line gene expression data." (PMID 23524533, 2013). "In accordance with these results, we suggest that pharmacokinetic behavior and tumor treating abilities of purvalanol A will not be affected by ABCG2 and/or ABCB1." (PMID 24116053, 2013). "ABCG2 protein expressions in 5% ethanol-treated SP cells and tumor tissues had no significant changes compared with ABCG2 expressions in each corresponding control." (PMID 24009622, 2013). "Surprisingly, at 4 weeks after inoculation, all groups of different amounts of ABCG2+ cells formed visible tumors in nude mice while ABCG2− cells failed to establish tumor when inoculated with less than 2 × 105 cells." (PMID 24194752, 2013). "As above for ABCG2 and ICAM4, we attribute the apparently low tumor-wide expression of L-Myc (MYCL1) to the possibility that in SCC it is robustly expressed only in CD133+ cells, which constitute a minor fraction of the tumor cells." (PMID 23527012, 2013). "No significant change was found in ABCG2 mRNA level after 5% ethanol treatment both in SP cells and in xenografts tumor cells." (PMID 24009622, 2013). "This situation mirrors that of CD133/PROM1, so we speculate that the apparently low tumor-wide expression of ABCG2 and ICAM4 is because they are robustly expressed only in CD133+ cells, which constitute a minor fraction of the tumor cells." (PMID 23527012, 2013). "The increase in ABCG2 mRNA after 2-DG or hypoxia treatment was blocked by actinomycin D (5 μg/mL; data not shown), suggesting that these tumor microenvironment conditions regulate ABCG2 mRNA levels through an effect on ABCG2 transcription." (PMID 22778999, 2012). "On the other hand, the cytotoxicity of cisplatin was not affected, indicating the specific effect of these tumor microenvironment conditions on ABCG2-mediated MDR." (PMID 22778999, 2012). "Because the expression levels of ABCG2, PEPT1, PEPT2 and ferrochelatase (FECH) are important factors that affect ALA-mediated PpIX accumulation, expression of these proteins were measured in several tumor cell lines by Western blotting analysis." (PMID 23189181, 2012). "This was still the case for topotecan, but not for irinotecan when tumor volume changes were analysed per individual ABCG2-positive tumor." (PMID 23028879, 2012). "Positive staining with ABCG2 and OCT4 was demonstrated on a mixed UM primary tumor." (PMID 22815634, 2012). "The expression of ABCG2 and P-glycoprotein (ABCB1) is also important for efflux of the Hoechst 33342 dye, a phenotypic characteristic that defines the “side population” of human tumor cells and stem cells." (PMID 24212632, 2011).
tumor (continued). "Interestingly, the expression of breast cancer resistance protein (BCRP/ABCG2), a well-known transporter of ATP-binding cassette (ABC) family involved in chemo-resistance, was detected in the recurrent tumor from this patient." (PMID 21731744, 2011). "The HIV-protease inhibitors (HIV-PIs) are substrates/inhibitors of the ABC transporters ABCB1, ABCG2, ABCC1, and ABCC2; induce and/or select for ABCB1 in human tumour cells; and sensitise cells to chemotherapeutics such as vincristine, vinblastine, and doxycycline in an HIV-PI-dependent manner." (PMID 21829205, 2011). "In the present study, we studied ABCG2 expression in paraffin-embedded tumor samples using the IHC method with the BXP-21 antibody, and the positive stain for ABCG2 is located in the cytoplasm and cytomembrane of cells as the product leaflet of the antibody indicates." (PMID 21943250, 2011). "ABCG2/BCRP1 (breast cancer-resistance protein-1), an ATP-binding cassette (ABC) transporter, is a cell surface drug-resistance marker as well, which has been used to identify stem cells from a variety of tissues, including tumours." (PMID 20354527, 2010). "On the other hand, an interesting question is why neither ABCG2+ nor CXCR6+ cells were detected in tumor xenografts." (PMID 21203549, 2010). "Cellular pumps like ABCG2, MDR1 or MRP1 can export a broad spectrum of molecules, including chemotherapeutics out of the cells, preventing them from killing the tumour cell." (PMID 17164759, 2007). "In this retrospective cohort study of patients with non-resectable PC, we examined whether tumor-tissue expression of drug efflux pumps ABCB1 and ABCG2 was associated with outcome of chemotherapy with gemcitabine and nab-paclitaxel." (PMID 40548120, 2025). "Furthermore, it has been shown that the expression of the ABCB1 and ABCG2 transporters at the endothelial cell luminal membrane in the BTB might be increased compared to the unaffected BBB and in tumor cells themselves." (PMID 40893689, 2025). "The literature reports that other ABC transporters (ABCC subfamily members, ABCG2) that may also be important in the development of doxorubicin resistance were not confirmed in our analysis of the NCI tumor panel." (PMID 40723843, 2025). "Interestingly, other ABC transporter genes that have been described to confer resistance in cell lines with acquired doxorubicin (e.g., ABCC1, ABCC2, and ABCG2) were not related to inherent anthracycline resistance in this panel of tumor cell lines." (PMID 40723843, 2025). "Additionally, studies suggest that the breast cancer resistance protein (BCRP, ABCG2) may be involved in cisplatin resistance by influencing drug accumulation in tumor cells." (PMID 41049434, 2025). "The function of the BBB and the corresponding density of the cell monolayer remains unchanged even during changes at the tumor site; therefore, small molecules, including drugs, can be secreted by efflux pumps such as P-glycoprotein (P-gp, ABCB1) or breast cancer resistance protein (BCRP, ABCG2)." (PMID 40574095, 2025). "However, the SP fraction's heterogeneity challenges interpretations, with ABCG2 identifying fast‐cycling tumor progenitors rather than exclusively CSCs." (PMID 39309691, 2024). "The ABCG2 profile was found to affect the overall patient survival (p = 0.02) and represent a moderate indicator of tumor progression (p = 0.01), unlike the percentage of ABCG2-positive tumor cells." (PMID 38542090, 2024). "ABCG2 mRNA expression was found to be lower in tumours than in normal colonic tissue." (PMID 38067326, 2023). "AMBL was found to express ABCG2, ALDH1, BMI1, CD133, CD166, CD44, and c-Myc in peripheral and/or central cells of the parenchyma at variable extent and intensity levels, as well as CD34 in spindle-shaped stomal cells and LGR5 and NANOG in both epithelial and stromal tumor components." (PMID 37761874, 2023).